ALDH1A1 (aldehyde dehydrogenase 1 family member A1)
Diseases named in the same sentence as ALDH1A1 in open-access papers (continued):
Sharing a sentence is not in itself a finding about the gene and the disease.
bladder cancer (27 papers, 2014 to 2025). "ALDH1A1, a recognized diagnostic target overexpressed in bladder cancer, and its downstream target TUBB3 can be degraded to reduce invasion and proliferation, providing new avenues for diagnosis and therapy in advanced disease." (PMID 41153362, 2025). "Bladder cancer patients with the high expression of ALDH1A1 were significantly associated with poor prognosis." (PMID 35342431, 2022). "A study using 3D cell cultures derived from patient bladder cancer cells found significant ALDH1A1 expression, a marker for stem cells." (PMID 40635786, 2025). "Secondly, in this study, the CD44+ALDH1A1+ subpopulation was referred to as bladder cancer stem-like cells, which is consistent with a previous study." (PMID 38191448, 2024). "The CD44+ALDH1A1+ subpopulation, which is referred to as bladder cancer stem cells (BCSCs), displayed enhanced tumor sphere formation and resistance to cisplatin." (PMID 38191448, 2024). "After shRNA was used to functionally knock down the ALDH1A1 gene, clonality and tumorigenicity of bladder cancer CSCs were reduced." (PMID 35903544, 2022). "It is also worthy to note that ALDH1A1 contributes to bladder cancer progression by increasing the expression of βIII-tubulin (TUBB3)." (PMID 35173149, 2022). "ALDH1A1+ bladder cancer cells had higher tumorigenicity than ALDH1A1− cancer cells both in vivo and in vitro." (PMID 35342431, 2022). "Clinical survival data suggest that TUBB3 expression correlates with poor prognosis in bladder cancer patients, indicating that ALDH1A1 and TUBB3 may serve as promising therapeutic targets." (PMID 40635786, 2025). "Furthermore, bladder cancer tissues with low LASS2 expression had a higher proportion of stem-like cells (CD44+ALDH1A1+)." (PMID 38191448, 2024). "The ALDH1A1+ bladder cancer cells can represent CSCs in bladder cancer." (PMID 35342431, 2022). "Notably, TUBB3 has been documented to be a downstream target of ALDH1A1 and can be positively regulated by ALDH1A1 in bladder cancer." (PMID 35173149, 2022). "Finally, the expression of β-catenin and some of the CSC markers analyzed in our study, such as ALDH1A1, Sox-2 or Oct-4, correlates with tumor grade, recurrence, metastasis or worse survival in patients with bladder cancer." (PMID 35008872, 2021). "It was reported that ALDH1A1 could upregulate TUBB3 to promote bladder cancer progression." (PMID 35173149, 2022). "Recently, a report also shows that atRA produced by ALDH1A1 transcriptionally activates functional RAREs in class III β‐tubulin (TUBB3) promoter, stimulating proliferation and sphere formation in patient‐derived bladder cancer cells." (PMID 36694633, 2023). "More interestingly, ALDH1A1+ cells were found to be a subtype of CD44+ cells, suggesting that such cells may be the more primitive bladder cancer CSCs." (PMID 35903544, 2022). "Additionally, ALDH1A1 can metabolize retinal RA, thus activating RAR-mediated transcription of downstream targets, such as TUBB3, in bladder cancer cells." (PMID 36387165, 2022).
gastric cancer (27 papers, 2008 to 2025). A primary or metastatic malignant neoplasm involving the stomach. "Collectively, the strong association of high ALDH1A1 expression with gastric cancer aggressiveness suggests that ALDH1A1 could be a feasible target for cancer therapy." (PMID 26783961, 2016). "Determination of ALDH1A1 expression may help to identify high-risk gastric cancer patients and thus aid the selection of appropriate therapies." (PMID 25253129, 2014). "Therefore, it appears that ALDH1A1 may serve as a powerful prognostic factor for patients with gastric cancer in different risk groups." (PMID 25253129, 2014). "By targeting ALDH1A1, miR-625 has been shown to reverse multidrug resistance in gastric cancer cells." (PMID 35992812, 2022). "We analyzed how the expression levels of Sox2 and ALDH1A1 individually correlate with overall survival in a total 116 gastric cancer patients with follow-up data." (PMID 28046028, 2017). "In this study, the expressions of ALDH1A1 and Sox2 were detected by immunohistochemistry in 122 gastric cancer specimens." (PMID 28046028, 2017). "The association between expression of ALDH1A1 and MMP-9, clinicopathological parameters, and prognosis of gastric cancer was examined." (PMID 25253129, 2014). "The aim of this study is to determine the relationship of ALDH1A1 expression with clinicopathological parameters and prognosis in gastric cancer." (PMID 25253129, 2014). "According to the results of immunohistochemistry, we correlated ALDH1A1 status in 216 gastric cancer specimens with clinicopathologic parameters." (PMID 25253129, 2014). "In the present study, we assessed the expression of ALDH1A1 in gastric cancer tissues by immunohistochemistry." (PMID 25253129, 2014). "We further explored the influence of tumor invasiveness on the prognostic value of ALDH1A1 expression in gastric cancer by using MMP-9 as an indicator for the invasive potential of individual tumor cells." (PMID 25253129, 2014). "Correlation of ALDH1A1 with clinicopathological parameters and survival of gastric cancer patients were then analyzed." (PMID 25253129, 2014). "To elucidate the biological significance of ALDH1A1 in gastric cancer, we examined the immunohistochemical expression of ALDH1A1 in gastric cancer tissues." (PMID 25253129, 2014). "Further investigation is necessary to clarify the role of ALDH1A1 in the development of gastric cancer." (PMID 25253129, 2014). "Our results showed that ALDH1A1 expression was a poor independent prognostic factor for OS in gastric cancer patients (hazard ratio, 2.037; 95% CI, 1.407 - 2.950)." (PMID 25253129, 2014). "In the present study, the expression of ALDH1A1 was investigated in 216 gastric carcinoma tissues by immunohistochemistry." (PMID 25253129, 2014). "Sixty percent (73/122) of gastric cancer samples showed ALDH1A1 positive expression." (PMID 28046028, 2017). "Therefore, we evaluated the expression of ALDH1A1 and Sox2 in gastric cancer samples, and, with respect to stratification, analyzed their correlation with pathological parameters and patient survival." (PMID 28046028, 2017). "In addition, survival times (overall survival and recurrence-free survival) of gastric cancer patients with high ALDH1A1 expression were significantly shorter than for those with low ALDH1A1 expression." (PMID 26783961, 2016). "Likewise, gastric cancer cells with high level of ALDH1A1 expression are more resistant to 5-FU and cis-diamminedichloroplatinium than those cells with lower level." (PMID 25788273, 2015). "Moreover, ALDH1A1 was significantly correlated with MMP-9 among 216 gastric cancer tissues (P < 0.001)." (PMID 25253129, 2014). "In addition, the Kaplan-Meier survival analysis revealed that the survival times (OS and RFS) of gastric cancer patients with high ALDH1A1 expression were significantly shorter than those with low ALDH1A1 expression." (PMID 25253129, 2014).
gastric cancer (continued). "In this study, we demonstrated that ALDH1A1 may play an important role in tumor invasion, metastasis and prognosis, and could work as a promising target for prognostic prediction in gastric cancer." (PMID 25253129, 2014). "The positive rate of ALDH1A1 was 50.0% (108/216) in gastric cancer samples." (PMID 25253129, 2014). "Collectively, ALDH1A1 status in gastric cancer promoting tumor aggressiveness suggests that ALDH1A1 could be a feasible target in cancer therapy." (PMID 25253129, 2014). "Therefore, the role of Sox2 and ALDH1A1 in gastric cancer remains nebulous." (PMID 28046028, 2017). "In addition, ALDH1A1 was significantly correlated with MMP-9 in 216 gastric carcinoma specimens." (PMID 25253129, 2014). "For example, DTCs of gastric cancer express various stem cell markers, such as LGR5, TROY and ALDH1A1, and ALDH1A1 can promote the formation of DTC of acute myeloid leukemia cells through up-regulating mTOR." (PMID 37483492, 2023). "To better understand the clinical significance of ALDH1A1 on aggressiveness in gastric cancer, we investigated the relationship of ALDH1A1 and MMP-9 protein expression in gastric cancer." (PMID 25253129, 2014). "However, the role of ALDH1A1 on the prognosis of patients with gastric cancer remains unclear." (PMID 25253129, 2014). "ALDH1A1 and matrix metallopeptidase 9 (MMP-9) was evaluated by immunohistochemistry in 216 gastric carcinoma samples." (PMID 25253129, 2014). "Although stemness-related factors ALDH1A1 and Sox2 have been used as markers to identify gastric CSCs, the expression pattern and significance of these factors in gastric cancer have not been sufficiently demonstrated." (PMID 28046028, 2017). "Furthermore, the multivariate Cox model analysis indicated that ALDH1A1 status was an independent factor for both prognosis indexes (OS and RFS) in gastric cancer." (PMID 25253129, 2014). "The postoperative median OS times in ALDH1A1-positive (n = 108) and ALDH1A1-negative (n = 108) gastric cancer patients subgroup were 12.0 months and 42.0 months, and the median of the RFS times were 9.0 months and 39.0 months." (PMID 25253129, 2014). "Therefore, the expression of ALDH1A1 appears to be a strong postoperative prognostic parameter for patients with gastric cancer independent of tumor invasiveness." (PMID 25253129, 2014). "Therefore, we also investigated the relationship of ALDH1A1 and MMP-9 protein in gastric cancer." (PMID 25253129, 2014). "In addition, Kaplan-Meier analysis demonstrated that ALDH1A1 overexpression (P < 0.001), larger tumor size (P = 0.001), tumor site (P = 0.047), prominent serosal invasion (P < 0.001) and lymph node metastasis (P < 0.001) were negative prognostic factors for RFS in gastric cancer patients." (PMID 25253129, 2014).
hepatocellular carcinoma (25 papers, 2007 to 2025). A malignant tumor that arises from hepatocytes. "One study showed that high levels of ALDH1A1 were associated with low serum α-fetoprotein levels, small tumor diameter and very little lymphatic vessel invasion in hepatocellular carcinoma." (PMID 38139832, 2023). "Another study found that high levels of ALDH1A1 were associated with longer survival in hepatocellular carcinoma." (PMID 38139832, 2023). "In fact, in cultured mouse hepatoma cells, retinoic acid caused feedback inhibition of ALDH1A1 expression, although retinoic acid receptor alpha acted as an activator: its partnering activator of the ALDH1A1 promoter, namely C/EBPβ, was repressed by retinoic acid." (PMID 37298333, 2023). "The favorable prognostic impact of high ALDH1A1 expression in tumor cells aligns with results from hepatocellular carcinoma studies, suggesting a broader relevance across primary liver cancers." (PMID 39744576, 2025). "In our study, we found increased levels of ALDH1A1 for hepatocellular carcinoma cell lines (HepG2) after treatment with WZ2 and WZ4, after 48 h of incubation." (PMID 38139832, 2023). "ALDH1A1 has been reported to be the dominant enzyme subtype determining ALDEFLUOR activity in hepatocellular cancer (HCC) and hepatoblastoma and was a differentially expressed protein in CD133+ and CD133– cells of the Huh7 and PLC8024 HCC cell lines." (PMID 36651035, 2023). "Thus at least in mouse hepatoma cells, the net effect of retinoic acid on the ALDH1A1 gene promoter was inhibition." (PMID 37298333, 2023). "Thence, these coated NPs showed the highest selective apoptosis-mediated toxicity only in murine hepatoma cells (Hepa) that may attribute to suppression of NF-κB expression and ALDH1A1 activity, subsequently collapsing 89.7% CD133+CSCs." (PMID 29545617, 2018). "For example, ALDH1A1 (stress response) and MAPK3 (cell proliferation) are targets of the HGF/MET signaling pathway which has been associated with tumor metastasis and poor prognosis in human hepatocellular carcinomas." (PMID 17900369, 2007). "Based on the results of our experiments and bioinformatic assay, the potential uses of ALDH1A1 in hepatocellular carcinoma (HCC) will be discussed." (PMID 35814382, 2022). "More interestingly, analysis of the Oncomine database showed that the expression of ALDH1A1 was significantly upregulated in the hepatocellular carcinoma (HCC) tissues than in the normal tissues." (PMID 34096467, 2021). "Hepatocellular carcinoma is a special case because the expression of many ALDH subtypes, including ALDH1A1, ALDH1L1, ALDH2, ALDH3A2, ALDH4A1, ALDH7A1, and ALDH9A1, is relatively high in this cancer." (PMID 36651035, 2023). "In hepatocellular carcinoma (HCC) and hepatoblastoma, ALDH1A1 has been described as the predominant isoform—the one dictating ALDEFLUOR activity—and it was found to have differential expression in CD133+/− HCC cell lines." (PMID 37686694, 2023). "However, the role of ALDH1A1 in hepatocellular carcinoma (HCC) has not been well elucidated." (PMID 26160842, 2015).
Parkinson disease (25 papers, 2012 to 2026). A progressive degenerative disorder of the central nervous system characterized by loss of dopamine producing neurons in the substantia nigra and the presence of Lewy bodies in the substantia nigra and locus coeruleus. "ALDH1A1 is highly expressed in the kidney and liver, and mutations of this enzyme have been associated with a number of human diseases, including cancer, Parkinson’s disease, and obesity." (PMID 36450445, 2023). "Expression of Aldh1a1, whose role is implicated in neuronal patterns, differentiation and survival is reportedly reduced in Parkinson’s disease, perhaps also consistent with a possible disease-causing influence in old age also." (PMID 34074801, 2021). "Thus, the effects of age and Aldh1a1/Aldh2-deficiency on spatial memory recapitulate the cognitive deficits seen in early stage Parkinson's disease." (PMID 22384032, 2012). "Thus, with respect to responsiveness to L-DOPA, the Aldh1a1/Aldh2-deficient mice model this aspect of Parkinson's disease." (PMID 22384032, 2012). "BACKGROUND: Motor symptoms of Parkinson’s disease (PD) primarily result from the degeneration of nigrostriatal dopaminergic neurons (DANs), particularly the Aldehyde Dehydrogenase 1A1-positive (ALDH1A1+) subpopulation." (PMID 41485044, 2026). "Aldehyde dehydrogenase 1A1-positive (ALDH1A1+) dopaminergic neurons (DANs) are preferentially vulnerable in Parkinson's disease (PD), yet how their activity is modulated by presynaptic inputs remains poorly defined." (PMID 42182513, 2026). "AEP is subsequently activated by α‐Syn fibrils in the SNpc, leading to cleavage of Sox6 and ALDH1A1 in SNpc DA neurons, contributing to the vulnerability of dopaminergic neurons in Parkinson's disease." (PMID 39573918, 2025). "Motor symptoms of Parkinson’s disease (PD) primarily result from the degeneration of nigrostriatal dopaminergic neurons (DANs), particularly the Aldehyde Dehydrogenase 1A1-positive (ALDH1A1+) subpopulation." (PMID 41472677, 2025). "DA neurodegeneration upon Parkinson disease occurs mainly in the SN where most Aldh1a1 positive DA neurons reside." (PMID 38704506, 2024). "Wdfy1 regulates neurite outgrowth and Aldh1a1 prevents neuronal degeneration in Parkinson’s disease." (PMID 34735454, 2021). "Aldehyde dehydrogenase 1 (ALDH1A1)–positive dopaminergic (DA) neurons at the ventral substantia nigra pars compacta (SNpc) preferentially degenerate in Parkinson’s disease (PD)." (PMID 28706191, 2017). "The ALDH1A1 enzyme was reported to be down-regulated in brain tissues affected by Parkinson’s disease and researchers investigated the role of ALDH1A1 in mediating HNE toxicity." (PMID 28205523, 2017). "In addition, it has been observed that the expression of ALDH1A1 is significantly reduced in the Parkinson’s disease brain in comparison with normal, healthy controls." (PMID 36450447, 2023). "Thus, this is consistent with the fact that, in Parkinson’s disease, ventral SNpcs with more ALDH1A1 positive neurons degenerate more severely and movement is more affected." (PMID 34200134, 2021). "Specific inhibitors have been sought for ALDH1A1, ALDH1A1, and ALDH1A3 for treatment of Parkinson’s disease, obesity, cataracts, and various types of cancer." (PMID 35796328, 2023). "Using a conditional mouse model with loss of ASL in catecholamine neurons, we demonstrate that ASL is expressed in dopaminergic neurons in the substantia nigra pars compacta, including the ALDH1A1 + subpopulation that is pivotal for the pathogenesis of Parkinson disease (PD)." (PMID 34417872, 2021). "Aldehyde dehydrogenase 1A1 (ALDH1A1), a retinoic acid (RA) synthase, is selectively expressed by the nigrostriatal dopaminergic (nDA) neurons that preferentially degenerate in Parkinson’s disease (PD)." (PMID 30837649, 2019).
glioblastoma (23 papers, 2015 to 2025). The most malignant astrocytic tumor (WHO grade IV). "This meta-analysis explores the associations of the use of potent ALDH1A1-activating proton pump inhibitors and other antacid drugs with survival outcomes in patients with newly diagnosed glioblastoma." (PMID 41288972, 2025). "High ALDH1A1 expression has been associated with poor prognosis in glioblastoma, and its overexpression in vitro a predictor of TMZ resistance." (PMID 29053791, 2017). "Translational research studies may explore whether PPI-induced activity of ALDH1A1 mediates a potential detrimental effect of PPIs in glioblastoma or whether other pathways are involved." (PMID 41288972, 2025). "The development of effective therapy for eradicating glioblastoma stem cells remains a major challenge due to their aggressive growth, chemoresistance and radioresistance which are mainly conferred by aldehyde dehydrogenase (ALDH)1A1." (PMID 38720782, 2024). "Furthermore, ALDH1A1 has been associated with glioblastoma proliferation and migration, while decreased ALDH1A1 expression could restore GBM cell sensitivity to temozolomide, a common and efficient chemotherapeutic drug for GBM." (PMID 35116021, 2021). "Proton pump inhibitors (PPIs) are often prescribed to manage corticosteroid-induced gastrointestinal toxicity during glioblastoma (GBM) treatment, but were recently identified as strong inducers of aldehyde dehydrogenase-1A1 (ALDH1A1)." (PMID 39554793, 2024). "Recently, nanocomplexes of diethyldithiocarbamate (DE), an inhibitor of aldehyde dehydrogenase 1A1 (ALDH1A1), conjugated with ferrous oxide nanoparticles (FeO NPs), demonstrated remarkable efficacy by inhibiting the growth, chemoresistance, and radioresistance of glioblastoma CSCs." (PMID 40143107, 2025).
head and neck squamous cell carcinoma (22 papers, 2011 to 2025). A squamous cell carcinoma that arises from any of the following anatomic sites: lip and oral cavity, nasal cavity, paranasal sinuses, pharynx, larynx, and salivary glands. "This is in line with a meta-analysis in head and neck squamous cell carcinoma, showing that high ALDH1A1 expression was associated with poorly differentiated tumors." (PMID 30308036, 2018). "The pharmacological inhibition of ALDH1A1 resulted in decreased formation of sphere-like colonies along with down regulation of cancer stem cell markers in head and neck squamous cell carcinoma cell lines." (PMID 28671577, 2017). "In head and neck squamous cell carcinoma (HNSCC), ALDH1A1 was enriched in cisplatin and 5-fluorouacil-resistant squamous cell carcinoma (SCC) Cal-27 cell lines, which displayed enhanced stemness features such as spheroid formation, clonogenicity, and migratory potential." (PMID 38612911, 2024). "ALDH1A1 is expressed in more than 10% of tumor cells in HNSCC tumor samples and in more than 25% of the cells in Fanconi anemia-head and neck squamous cell carcinoma (FA-HNSCC) tumor tissue samples." (PMID 37686694, 2023).